SLC25A21 (solute carrier family 25 member 21)
Description:
Transports dicarboxylates across the inner membranes of mitochondria by a counter-exchange mechanism. Can transport 2-oxoadipate (2-oxohexanedioate), 2-oxoglutarate, adipate (hexanedioate), glutarate, and to a lesser extent, pimelate (heptanedioate), 2-oxopimelate (2-oxoheptanedioate), 2-aminoadipate (2-aminohexanedioate), oxaloacetate, and citrate. Plays a central role in catabolism of lysine, hydroxylysine, and tryptophan, by transporting common metabolite intermediates (such as 2-oxoadipate) into the mitochondria, where it is converted into acetyl-CoA and can enter the citric acid (TCA) cycle (Probable).
Synonyms: ODC; ODC1; MTDPS18
Tractability: Antibody: UniProt predicts a signal peptide or a membrane-spanning region. PROTAC: a small molecule that binds it is known.
Gene: Protein-coding gene on chromosome 14 (36,677,921 to 37,172,606, reverse strand). Ensembl gene ENSG00000183032.
Subcellular location: Mitochondrion inner membrane
Pathways (Reactome):
Metabolism: Lysine catabolism
Gene Ontology:
Molecular function: alpha-ketoglutarate transmembrane transporter activity
Biological process: mitochondrial alpha-ketoglutarate transmembrane transport; L-lysine catabolic process; transmembrane transport
Cellular component: mitochondrion; mitochondrial inner membrane
Genetic constraint (gnomAD): Loss-of-function variants: 28 observed, 24.78 expected, observed/expected ratio (o/e) 1.13, 90% interval 0.84 to 1.55. The upper end of that interval is the gene's LOEUF score, 1.55, which puts it in group 6 of 6, group 1 being the genes least tolerant of losing a copy. Missense variants: 243 observed, 233.9 expected, observed/expected ratio (o/e) 1.04, 90% interval 0.94 to 1.15. Synonymous variants: 90 observed, 83.33 expected, observed/expected ratio (o/e) 1.08, 90% interval 0.91 to 1.29.
Homologues: Orthologues: chimpanzee SLC25A21 (99% identical), pig SLC25A21 (93% identical), guinea pig SLC25A21 (92% identical), macaque SLC25A21 (92% identical), dog SLC25A21 (91% identical), rabbit SLC25A21 (89% identical), mouse Slc25a21 (81% identical), rat Slc25a21 (79% identical), tropical clawed frog slc25a21 (79% identical), zebrafish slc25a21 (77% identical), Drosophila melanogaster CG5254 (57% identical), Caenorhabditis elegans slc-25A21 (57% identical), and 1 more. Paralogues in human: SLC25A13 (31% identical), SLC25A12 (29% identical), SLC25A22 (29% identical), SLC25A18 (28% identical), SLC25A48 (28% identical), SLC25A1 (28% identical), SLC25A45 (27% identical), SLC25A20 (27% identical), UCP1 (26% identical), UCP2 (26% identical), SLC25A29 (26% identical), SLC25A39 (26% identical), and 37 more.
Diseases named in the same sentence as SLC25A21 in open-access papers:
SLC25A21 is named in the same sentence as 26 diseases in open-access papers, as found by Europe PMC text mining. Sharing a sentence is not in itself a finding about the gene and the disease. The quoted sentences say what the papers report.
bladder cancer (4 papers, 2021 to 2024). "Studies suggested that SLC25A21 was associated with the prognosis of glioma, bladder cancer (BCa) and colorectal cancer (CRC)." (PMID 39706835, 2024). "A recent study revealed that SLC25A21 suppresses cell growth and plays a pathogenic role on bladder cancer." (PMID 36246603, 2022). "After compiling the data, we would like to first point out that suppressing the expression of the efflux transporters ABCB1, ABCC2, SLC25A21, and ATP7A has been linked to cisplatin’s accumulation and reduced resistance in urinary bladder cancer patients." (PMID 36650399, 2023). "Interestingly, a recent study showed that SLC25A21 is a key tumor suppressor gene in bladder cancer." (PMID 36246603, 2022). "We concluded that the efflux transporters ABCB1, ABCC2, SLC25A21, ATP7A, and the uptake transporter OCT2, as well as the organic anion uptake transporters OAT1 and OAT2, are linked to cisplatin accumulation, toxicity, and resistance in urinary bladder cancer patients." (PMID 36650399, 2023).
glioma (4 papers, 2021 to 2025). A benign or malignant brain and spinal cord tumor that arises from glial cells (astrocytes, oligodendrocytes, ependymal cells). "Research has also noted a relationship between methylation patterns at CpG sites targeting SMOC1, KCNA4, SLC25A21, and UPP1, and the molecular characteristics of glioma, such as IDH mutations and 1p/19q co‐deletions, which aligns with our findings." (PMID 40781854, 2025). "SLC25A21 hypermethylation was correlated with poorer prognosis of Glioma patients." (PMID 39706835, 2024). "Our study highlights genes (KCNA4 and SLC25A21) that were not previously associated with gliomas to have contributed to the poorer patient outcome." (PMID 33498463, 2021). "The forest plot shows that EPB41L4A.AS1, GDNF.AS1, HAR1A, LINC00237, SLC25A21.AS1, SNA13.AS1, and WDFY3.AS2 are the protective factors with HR < 1, while LINC00092, LINC00265, LINC00339, LINC00665, PAXIP1.AS2, SNHG16, SNHG9 and SOCS2.AS1 are risk factors with HR>1 in glioma patients." (PMID 35273128, 2022). "CpG site of UPP1 demethylate as glioma grade increases while the remaining genes, SMOC1, KCNA4, and SLC25A21, methylate along with higher tumor grade." (PMID 33498463, 2021).
acute myeloid leukemia (3 papers, 2022 to 2024). Acute myeloid leukemia (AML) is a group of neoplasms arising from precursor cells committed to the myeloid cell-line differentiation. "A recent study demonstrated that low expression of SLC25A21 predicted unfavorable prognosis in patients with acute myeloid leukemia." (PMID 37937641, 2023).
colorectal cancer (2 papers, 2023 to 2025). A primary or metastatic malignant neoplasm that affects the colon or rectum. "SLC25A21, an αKG transporter in mitochondria, has been reported to affect the activity of the jmjC-type DNA demethylase TET in KRAS-mutant colorectal cancer." (PMID 41227300, 2025).
lung carcinoma (2 papers, 2021 to 2022). "Harris and colleagues first reported that the deletion of SLC25A21 appears to be associated with lung cancer." (PMID 34568013, 2021). "Deletion of the 14q13.3 region, which contains the SLC25A21 gene, has also been reported in lung cancer." (PMID 34568013, 2021).
migraine (2 papers, 2021 to 2025). "CPS1 rs1047891, PBRM1 rs11718509, and SLC25A21 rs10150336 were significantly associated with migraine in women (P < 5.0 × 10−8) but not in men (P > 0.05)." (PMID 34294844, 2021). "The women-specific (GERA + UKB) meta-analysis (22,500 migraine cases and 279,762 controls) identified 19 loci (P < 5.0 × 10−8), of which three, CPS1 on chromosome 2, PBRM1 on chromosome 3, and SLC25A21 on chromosome 14, were additional novel loci." (PMID 34294844, 2021). "Among the sex-specific loci associated with migraine susceptibility in women but not in men, less is known about the role of the identified CPS1 and SLC25A21 in regard to the biologic pathways underlying migraine." (PMID 34294844, 2021).
Obesity (2 papers, 2024). Accumulation of substantial excess body fat. "We highlighted the novel genes SLC25A21 and PAX9 on 14q13.3, also identified in the GWAS after adjusting for the BMI, supporting the notion that the genetic architecture of snoring was partly not explained by obesity." (PMID 38461358, 2024).
breast carcinoma (1 paper, 2015). "Only 10 featured genes were found (excluding NARS and SLC25A21) in the 27K datasets; these genes were used to predict breast cancer outcomes." (PMID 26550991, 2015).
cerebellar ataxia (1 paper, 2014). A neurological syndrome characterized by clumsy and uncoordinated movement of the limbs, trunk, and cranial muscles. "It has been proposed that loss of function of ODC, the protein encoded by SLC25A21, causes the human disease 2-oxoadipate acidaemia which is clinically characterised by hypotonia, seizures, motor and developmental delay, cerebellar ataxia and varying severities of intellectual disability." (PMID 24642684, 2014).
mastitis (1 paper, 2022). Inflammation of breast tissue during lactation or postpartum due to an obstructed duct or infection. "The hypomethylation and up-regulated expression of SLC25A21 in S. uberis-positive group in this study suggest that its altered expression during S. uberis mastitis may be regulated by DNA methylation changes." (PMID 36336691, 2022).
nasopharyngeal carcinoma (1 paper, 2023). A carcinoma arising from the nasopharyngeal epithelium. "Gene expression analysis showed that SLC25A21 was downregulated in 2 of 7 nasopharyngeal carcinoma cell lines." (PMID 37937641, 2023). "One study preliminarily found that SLC25A21 expression is aberrant in nasopharyngeal carcinoma cell lines." (PMID 37937641, 2023).
virus infection (1 paper, 2015). "And, virus infection was closely associated with SLE, indicating the potential role of SLC25A21 in SLE." (PMID 26509176, 2015).
cancer (9 papers, 2019 to 2024). A tumor composed of atypical neoplastic, often pleomorphic cells that invade other tissues. "However, the precise biological functions of SLC25A21 and the mechanisms underlying its dysregulation in cancer remain largely unknown." (PMID 37937641, 2023). "Collectively, these data indicate that SLC25A21 inhibits cancer cell growth and metastasis by repressing the KRAS/AKT/ERK pathway in KRAS-mutant CRC." (PMID 37937641, 2023). "Cell invasion analysis demonstrated that the exogenous SLC25A21 overexpression in two different BCa cell lines significantly inhibited cancer cell invasion through Matrigel, a basement-membrane- like extracellular matrix (P<0.001)." (PMID 34568013, 2021). "To further confirm the levels of SLC25A21 expression in BCa, we also analyzed the SLC25A21 expression in public datasets from The Cancer Genome Atlas (TCGA) and the Gene Expression Omnibus (GEO) database." (PMID 34568013, 2021). "We also found multiple cancer-specific edgetic perturbation biomarkers such as the SLC25A21 distortion in LUAD." (PMID 32152446, 2020). "In recent years, the roles of SLC25A21 in some cancers have been reported." (PMID 39706835, 2024). "Together, these data indicate that SLC25A21 selectively affects KRAS-mutant cancer cells." (PMID 37937641, 2023). "However, little is known about the potential role of SLC25A21 in cancer, especially BCa." (PMID 34568013, 2021). "However, the potential role of SLC25A21 in cancer remains absolutely unknown." (PMID 34568013, 2021). "Although the impact of SLC25A21 on cancer has not been evaluated, the vast number of studies done on other members of the SLC25 family implies that SLC25A21 can also be a promising tumor-associated marker." (PMID 33498463, 2021). "By analyzing the TCGA, we also found that SLC25A21 was lower expressed in transcript levels in BCa than in normal bladder mucosa according to a Gene Expression Profiling Interactive Analysis website (GEPIA) (gepia.cancer-pku.cn/)." (PMID 34568013, 2021).
tumor (7 papers, 2021 to 2025). "At the same time, HE staining of the subcutaneous tumor tissues also confirmed that the overexpression of SLC25A21 was associated with inhibited cellular proliferation." (PMID 39706835, 2024). "The SLC25A21 immunoreactivity scores showed that the lower levels of SLC25A21 expression were associated with tumor invasion and T stage." (PMID 34568013, 2021). "We found that the tumor volume and mass in nude mice subcutaneously injected with SLC25A21-overexpressing Kasumi-1 and THP-1 cells were significantly reduced compared with the control group." (PMID 39706835, 2024). "The protein levels of SLC25A21 from subcutaneous tumor tissues of nude mice was also examined using WB." (PMID 39706835, 2024). "They further identified that SLC25A21 dysregulation plays an important role in rewiring tumor metabolism in KRAS-mutant CRC." (PMID 39706835, 2024). "In contrast, the knockdown of SLC25A21 expression in HCT116 cells significantly accelerated xenograft tumor growth in nude mice and increased the Ki-67 index in xenografts." (PMID 37937641, 2023). "To further confirm our in vitro findings, we evaluated the effects of SLC25A21 on xenograft tumor growth in vivo." (PMID 37937641, 2023). "Collectively, the in vivo data indicate that SLC25A21 plays an important inhibitory role in tumor growth and metastasis, consistent with the results from in vitro assays." (PMID 37937641, 2023). "In summary, our data illustrate the importance of SLC25A21 dysregulation in rewiring tumor metabolism in KRAS-mutant CRC and inform therapeutic strategies for targeting CRC with KRAS mutation." (PMID 37937641, 2023). "SLC25A21 overexpression severely arrested tumor growth in mice injected with M5 cells, whereas tumor growth continued unabated in mice injected with control cells (P< 0.0001)." (PMID 37937641, 2023). "Our results identified that SLC25A21 acts as a tumor suppressor results from the overexpression of SLC25A21 inhibits cell growth and facilitates cell apoptosis in BCa in vitro and in vivo." (PMID 34568013, 2021). "Restoring SLC25A21 expression reduced KRAS signaling and sensitized CRC tumours to cetuximab, suggesting that targeting SLC25A21 could enhance therapeutic efficacy." (PMID 41154605, 2025). "Collectively, these results suggested that SLC25A21 is able to suppress tumor growth in vivo." (PMID 39706835, 2024). "Our studies demonstrate that SLC25A21 plays a significant role as a tumor suppressor in KRAS-mutant CRC by antagonizing Gln-dependent anaplerosis to limit GTP availability for KRAS activation, which suggests potential alternative therapeutic strategies for KRAS-mutant CRC." (PMID 37937641, 2023). "Although SLC25A21, EGFR, and COL1A2 are linked to tumour-associated signalling pathways, the precise mechanisms of this synergy remain unclear." (PMID 36246603, 2022). "Moreover, the enhanced SLC25A21 expression significantly suppressed tumor growth in a xenograft mouse model." (PMID 34568013, 2021). "Thus, we tested whether the overexpression of SLC25A21 in vivo suppressed tumor growth inhibition, using xenograft experiments." (PMID 39706835, 2024). "Thus, our study provides strong evidence supporting the tumor suppressor roles of SLC25A21 in BCa." (PMID 34568013, 2021). "The increased glutamine metabolism resulting from SLC25A21 downregulation provides substrates for GTP synthesis, maintaining persistent KRAS activation and promoting tumour progression." (PMID 41154605, 2025).
infection (3 papers, 2022 to 2024). The state of being infected such as from the introduction of a foreign agent such as serum, vaccine, antigenic substance or organism. "We used lentivirus-mediated infection to stably overexpress SLC25A21 in AML cell lines Kasumi-1 and THP-1." (PMID 39706835, 2024). "SLC25A21 has been reported as differentially expressed in mammary gland tissue following infection by E. coli and S. aureus." (PMID 36336691, 2022). "Moreover, we knocked down SLC25A21 expression in KRAS-mutant HCT116 and SW480 cells and in KRAS-WT HT29 cells, which have relatively high endogenous expression, by infection with a lentiviral vector harboring shRNA-SLC25A21." (PMID 37937641, 2023).
kidney (1 paper, 2024). "The regulation of Slc25a21 on representative enzymes involved in TCA cycle was confirmed in a separate in vivo AKI kidney model following high-pressure tail-vein injection of Slc25a21 plasmids, and in vitro using acutely injured TKPTS cells." (PMID 39695098, 2024).
SLC25A21 also shares sentences with these, for which no sentence is quoted: acute kidney injury (1 paper); brain tumors (1); developmental delay (1); immune disease (1); Intellectual disability (1); kidney damage (1); leukemia (1); oligodendroglioma (1); otitis media (1); pancreatic ductal adenocarcinoma (1).